RNU4-48P (RNA, U4 small nuclear 48, pseudogene)
Gene: Small nuclear RNA gene on chromosome 2 (127,472,234 to 127,472,415, forward strand). Ensembl gene ENSG00000202429.
Homologues: Orthologues: chimpanzee U4 (98% identical), macaque U4 (68% identical), tropical clawed frog U4 (47% identical), rat LOC120095803 (46% identical), tropical clawed frog U4 (43% identical), dog U4 (42% identical), tropical clawed frog U4 (41% identical), rabbit U4 (37% identical), rat LOC120097640 (36% identical), mouse Gm26425 (35% identical), mouse Gm55605 (35% identical), mouse Gm22956 (33% identical), and 1 more. Paralogues in human: RNU4-25P (43% identical), RNU4-77P (43% identical), RNU4-82P (43% identical), RNU4-30P (42% identical), RNU4-39P (42% identical), RNU4-6P (42% identical), RNU4-79P (42% identical), RNU4-9P (42% identical), RNU4-74P (42% identical), RNU4-86P (42% identical), RNU4-29P (41% identical), RNU4-55P (41% identical), and 81 more.